CYP3A4 (cytochrome P450 family 3 subfamily A member 4)
Diseases named in the same sentence as CYP3A4 in open-access papers (continued):
Sharing a sentence is not in itself a finding about the gene and the disease.
cancer (continued). "Piperine is a chemopreventive agent that inhibits P-glycoprotein and/or CYP3A4; therefore, it increases the bioavailability of drugs that are the substrate for PGP/CYP3A as well as increasing the sensitivity of cancer cells at the site of tumors." (PMID 34834336, 2021). "In Hp+-AG-IM network the expression of APOA4, GCG, CYP3A4, XPNPEP2 and FOXP3, JUN were statistically different in the comparison of normal and cancer in TCGA database." (PMID 32547867, 2020). "It is worth noting that the expression of APOA4, GCG, CYP3A4, XPNPEP2, and FOXP3, JUN were different between cancer and normal samples in TCGA database." (PMID 32547867, 2020). "Cyclophosphamide (CPA), a prodrug used in cancer therapy, is activated by CYP2C19, CYP2C9, CYP3A4, and CYP2B6 to treat some autoimmune disorders." (PMID 31998435, 2020). "Metabolic pathways involving cytochrome P450 3A4 (CYP 3A4) and P-glycoprotein (Pgp) must be taken into account in cancer patients as several cancer treatments and anticoagulants are metabolized through common pathways." (PMID 30621020, 2019). "Across 5 cancer types, 109 patients who received paclitaxel exhibited activation of NR1I2, many with concurrent activation of CYP2C8 or CYP3A4 – known members of paclitaxel’s metabolic pathway." (PMID 29783934, 2018). "Furthermore, everolimus dosing in cancer is much higher than in transplant patients (i.e. 5–10 mg/day versus 2-5mg/day), thus, it is conceivable that in the cancer setting, CYP3A4*22 might exert a greater and more clinical relevant effect on drug toxicity than in the transplant setting." (PMID 28727815, 2017). "We next examined the effect of TNC, EE2, and their combination in human liver (HepG2) and colon (LS174T) carcinoma cell lines containing the full-length PXR and the CYP3A4-XREM luciferase reporter plasmids." (PMID 26333997, 2015). "Rivory and colleagues demonstrated that cancer patients with elevated acute phase proteins, including CRP and alpha-1 acid glycoprotein (AAGP), had reduced CYP3A4 function as determined by the erythromycin breath test." (PMID 19450285, 2009). "The increased expression of CYP3A4 and CYP2E1 further suggests improved metabolic activity and functional maturation, which contribute to reduced proliferation and migratory behavior of the cancer cells." (PMID 41244070, 2025). "Sinapic acid is a potent anti-oxidant used for the treatment of cancer, infections, oxidative stress, and inflammation; its anti-cancer mechanism works through the regulation of multiple proteins (CTNNB1, PRKCA, CASP8, SIRT1) and cytochrome enzymes (CYP1A1, CYP3A4)." (PMID 38999065, 2024). "This alteration (30% reduction in hepatic and intestinal CYP3A4 expression) has been investigated in a PBPK study demonstrating a better prediction of exposure to sensitive CYP3A4 substrates (namely, midazolam and simvastatin) in patients with cancer." (PMID 38140068, 2023). "To elucidate the contribution of CYP3A4 to the KCa1.1 inhibition-induced overcome of DOX resistance in cancer spheroid models, we examined the effects of treatment with 10 μM PAX for 12 and 36 h on the expression levels of CYP3A4 transcripts and proteins, respectively." (PMID 37958656, 2023). "Collectively, the present results indicate that the up-regulation of CYP3A4 is responsible for the acquisition of DOX resistance in cancer spheroid models, and the inhibition of KCa1.1 overcame DOX resistance by repressing CYP3A4 transcription mainly through the Akt-Nrf2-CEBPB axis." (PMID 37958656, 2023). "Subsequent alterations in the cancer cells’ response to chemotherapy can occur through modulation of chemoresistance markers and hepatocyte metabolic enzymes such as cytochrome P450 (CYP450), primarily the CYP3A4 subgroup." (PMID 34262860, 2021). "We observed that glucose upregulated CYP3A4 mRNA in each case; however, the effect in human primary hepatocytes was not significant and was very modest compared to that in the cancer cell lines tested." (PMID 28436464, 2017).
cancer (continued). "A series of genes (e.g. CYP1A2, CYP3A4, CYP19A1), related to cancer in Cytochrome P450 Family, were down-regulated, with the exception of CYP2E1, which was up-regulated and may be involved in carcinogenic process of cervical cancer." (PMID 28225065, 2017). "Many anti-cancer drugs are metabolised by cytochrome P450 (CYP) enzymes, and especially CYP3A4." (PMID 27756298, 2016). "In this study, we characterized several extracts of traditional Chinese medicine (TCM) plants (N = 16) for their interaction with ABC transporters, cytochrome P3A4 (CYP3A4), and glutathione-S-transferase (GST) activities and their cytotoxic effect on different cancer cell lines." (PMID 26346937, 2015). "The interaction found in PK profiles of lapatinib and paclitaxel is consistent regardless of the cancer type, and such interaction was considered to be the result of lapatinib being a weak metabolism-dependent inhibitor of CYP3A4." (PMID 25967286, 2015). "If functionally active CYP3A4 enzymatic activity was present in RMS cancer tissue, then the enzyme could permit cancer cells to metabolize substrates, such as cyclophosphamide or ifosphamide, which are activated by CYP3A." (PMID 24699256, 2014). "In human cancer hepatic cell line HepG2, lansoprasole but not omeprazole induced CYP3A4 mRNA and protein, and the induction of CYP3A4 protein was enantiospecific with much stronger effects for S-LAN." (PMID 25141173, 2014). "Nevertheless, the impact on cancer risk of polymorphisms of the CYP enzymes with the broader substrate specificity, namely CYP3A4 and CYP3A5, has not been analyzed in detail so far." (PMID 17605821, 2007). "The MAT methodology did not allow for an estimation of the contribution of intestinal transporter-based DDIs to the variation in drug exposure, since the vast majority of small oral molecules in cancer studies are substrates of enzymes (mostly CYP3A4) without intravenous pharmacokinetic data." (PMID 36432682, 2022). "We found that four genes are highly expressed in HCC, among which four genes, CCNB1, CNB2, CDK1, and CYP3A4, are highly expressed in tumors, while CCNB1, CCNB2, and CDK1 are highly expressed in almost all cancer types, which may be involved in the important tumorigenesis or progression." (PMID 34337056, 2021). "CYP3A4 and CYP8B1 are the members of cytochrome P450 family which may rely on the function of metabolic carcinogens to play a vital role in chemoprevention, carcinogenesis, cancer therapy and metastasis." (PMID 34257549, 2021). "Interestingly, we did not observe induction of CYP3A4 mRNA in intestinal human cancer cell line LS174T by neither compound tested." (PMID 25141173, 2014). "Notably, reports showed that Sal B could inhibit CYP1A2 and CYP3A4 mRNA expression and induce GST protein expression, indicating that Sal B may be a protective compound against cancer." (PMID 23662152, 2013). "The present study is the first to support the notion that the inhibition of KCa1.1 may manipulate CYP3A4, which is involved in the metabolism of many anti-cancer drugs and revealed the KCa1.1 inhibition-mediated overcoming DOX resistance in KCa1.1 overexpressing cancer spheroid models." (PMID 37958656, 2023). "Although not justifiable in itself as a therapeutic strategy, the status of apigenin as an inhibitor of CYP1A2, CYP2C9 and CYP3A4 means that it may enhance rather than inhibit the action of certain cancer medications by altering their pharmacokinetics in a beneficial way." (PMID 34084146, 2021). "We used the well-known effector of CYP3A4 ANF, the non-selective tyrosine kinase inhibitor Gefitinib, used in cancer therapy, and the anti-inflammatory natural compound Schisandrin A." (PMID 35740978, 2022).
tumor (115 papers, 1998 to 2026). "Primary resistance is linked to intrinsic tumor cell factors, including the overexpression of CYP3A4 and the activation of FLT3 ligand; secondary resistance is associated with de novo FLT3 mutations and the aberrant activation of downstream signaling pathways." (PMID 39963240, 2025). "Better diagnostic methods for identifying particularly aggressive tumours, e.g. by new molecular markers, analysis of DNA ploidy or CYP3A4 genotype, would increase the effectiveness of AS on account of the reduced number of PC deaths due to under staging." (PMID 24721557, 2014). "Efforts should be made to design methods capable to cause a local inhibition of the tumour CYP3A4 enzyme." (PMID 12237780, 2002). "Likewise, the CYP3A4 SNP rs35599367 was significantly associated with age at first pregnancy (p-value = 0.009) and tumor stage (p-value = 0.04)." (PMID 31477036, 2019). "Also, CYP3A4 overexpression in adjacent bone specimens was associated with good response (tumor necrosis grade higher than 90% - grades III and IV) (p=0.0484) and conservative surgery (p=0.0329) (respectively)." (PMID 28404946, 2017). "This study further expands on previous experiments from our group in which a transgenic mouse model of human CYP3A4 regulation was used to demonstrate that the presence of tumour resulted in downregulation of the CYP3A4 transgene, which was linked to a systemic acute phase response." (PMID 18059400, 2008). "Research has demonstrated that increased expression of CYP3A4 mRNA in tumor tissues can accelerate drug metabolism, potentially leading to reduced efficacy or even resistance to the treatment." (PMID 39931465, 2025). "Slides 17 and 18 show positive staining of the tumor cells for CYP3A4, which is involved in the metabolism of idarubicin, cytarabine, as well as venetoclax." (PMID 40142797, 2025). "CYP3A4 can convert mitotane into inactive metabolites, reducing the drug’s effective concentration in the plasma and tumor tissue." (PMID 39682247, 2024). "Our study revealed that the expression levels of NAV1, EHMT2, SP1, SLC6A4, OPRD1, and CYP3A4 between the normal and tumor were statistically significant." (PMID 38352696, 2024). "Increased expression of CYP2C8 and/or CYP3A4 and the high paclitaxel-metabolizing activity of tumour cells are also assumed to be developed as a consequence of the multiplication of CYP copy numbers." (PMID 37686184, 2023). "TsIIA can up regulate the expression of CYP3A4 protein, reduce tumor volume, reduce serum AST level, and thus improve the quality of life." (PMID 36798821, 2023). "Sorafenib metabolism was shown to be significantly decreased in tumor hepatic microsomes together with the downregulation of CYP3A4 and UGT1A9 expression." (PMID 36035299, 2022). "Linoleic acid metabolism is mediated by cytochrome P450 (CYP1A2, CYP2C, CYP2J, CYP2E1, and CYP3A4) to proinflammatory and proangiogenic oxylipins resulting in tumor growth or metastasis." (PMID 35155234, 2022). "CYP3A4 immunoreactivity proved to be significantly lower in tumor tissues than in a benign epithelium; diminished immunoreactivity of CYP3A4 correlated with a poor prognosis of the disease." (PMID 36359206, 2022). "These highlights the potential clinical significance of infigratinib‐induced cell differentiation, where tumours with higher expression of HNF4α, albumin and CYP3A4 were less proliferative, therefore reducing disease progression and improving overall survival." (PMID 33179425, 2021). "Infigratinib‐treated tumours showed higher expression of the differentiation markers CYP3A4, HNF4α and albumin, indicating a reduction in stemness." (PMID 33179425, 2021). "Overexpression of CYP3A4 in tumor tissues and chemoresistance to therapeutics has been shown in clinical practices." (PMID 34262860, 2021). "Tumour sections were stained for markers of hepatocyte differentiation, such as CYP3A4, HNF4α and albumin." (PMID 33179425, 2021).
tumor (continued). "This highlights a potential mechanism of differential tumor chemoresistance through the modulation of CYP3A4 under different microenvironmental conditions." (PMID 34262860, 2021). "CYP3A4 is often highly expressed in drug-resistant tumor samples, and the inhibition of CYP3A4 activity is a considerable part for solving the drug resistance of tumor cells." (PMID 32792861, 2020). "Other authors describe that extracts derived from different plants, exhibit an anticancer activity on different tumor cell lines, also modulating the expression and function of CYP3A4." (PMID 30999678, 2019). "A more recent study showed that CYP3A4 expression was significantly higher in tumor tissue when compared with normal lung tissue." (PMID 31309254, 2019). "The GEP analysis showed that the down-regulated genes in tumor tissue were CYP3A4 in 56 patients (61%), CYP2C8 in 44 patients (48%), CYP2C19 in 30 patients (33%), CYP2D6 in 11 patients (12%), CYP3A5 in 7 patients (8%) and CYP1B1 in 2 patients (2%)." (PMID 29774122, 2018). "Looking closely at the SCC-820 genes that were frequently up-regulated or down-regulated in tumor tissue, especially those that were down-regulated—in addition to CYP3A4—both CYP2C8 and CYP2C19 were included in the top thirty genes." (PMID 29774122, 2018). "Since CYP3A4 is mainly distributed in the liver and intestine organs, we used the two human tumor cell lines." (PMID 30594244, 2018). "The genes found to be down-regulated in tumor tissue were CYP3A4 in 56 patients (61%), CYP2C8 in 44 patients (48%), CYP2C19 in 30 patients (33%), CYP2D6 in 11 patients (12%), CYP3A5 in 7 patients (8%) and CYP1B1 in 2 patients (2%)." (PMID 29774122, 2018). "CYP3A4 in tumor and non-tumor samples have Ct mean<35, while CYP3A5 showed Ct means of 35.6 in normal tissue and 33.4 in tumor samples." (PMID 24699256, 2014). "CYP3A4 mRNA transcripts were quantifiable in 7 out of 13 normal tissue samples (53.8%) and in 9 out of 13 tumor samples (69.2%)." (PMID 24699256, 2014). "By utilising a regulatory transgenic reporter mouse model of human CYP3A4, Charles and colleagues demonstrated that the presence of tumour resulted in down-regulation of the CYP3A4, which correlated with a systemic acute phase response." (PMID 19450285, 2009). "Members of the ATP-binding cassette superfamily of proteins (ABCB1 and ABCG2) function to export irinotecan from tumour cells, while drug metabolism via the cytochrome P450 system (CYP3A4) or glucuronidation (UGT1A1) can also occur." (PMID 15655543, 2005). "RT-PCR showed that both CYP3A5 mRNA and CYP3A7 mRNA were consistently present in both tumour and normal samples, while CYP3A4 mRNA was present in 65% of tumours and 90% of normal samples." (PMID 10206301, 1999). "PTE is rapidly metabolized by hepatic cytochrome P450 enzymes (CYP1A2, CYP2C9, and CYP3A4) 48, and the tumor microenvironment may further hinder its penetration and activity." (PMID 40520023, 2025). "Increased methylation in the promoter regions of CYP3A4 may result in reduced enzyme expression, particularly in tumor cells." (PMID 39931465, 2025). "Future studies should examine whether a “CYP3A4 threshold” exists, beyond which its tumor-promoting activities outweigh its compensatory benefits in GGA biosynthesis." (PMID 41142201, 2025). "Biomarker studies focusing on CYP3A4 mRNA levels or protein expression in tumor biopsies could aid in stratifying patients and predicting treatment outcomes." (PMID 39682247, 2024). "We first detected the expressions of CYP3A4 in normal and tumor breast cell lines." (PMID 38215156, 2024). "Altogether, 224 overexpressed genes were identified in the tumor samples derived from the patients without PCR; among these, the gene sets associated with xenobiotic metabolism (e.g., CYP3A4, CYP2A6) exhibited significant enrichment." (PMID 38256136, 2024). "CYP3A4 expression within tumor tissue itself can contribute to localized drug resistance." (PMID 39682247, 2024).
tumor (continued). "Additionally, according to some data obtained by immunohistochemistry, in the stroma and glandular tissue of a mammary gland containing a tumor, CYP3A4 is overexpressed as compared to the healthy tissue." (PMID 36359206, 2022). "Hence, we evaluated the inhibitory effects of diflavonoids toward three clinical drugs that mainly undergo CYP3A4-mediated metabolism including anticoagulant agent ticagrelor, anti-tumor drug tamoxifen, and gefitinib." (PMID 35295338, 2022). "Meanwhile, the methylation level of ESR1 and CYP3A4 in tumor samples was significantly higher than that in normal samples, implying that methylation could be one of the factors leading to abnormal gene expression." (PMID 35356272, 2022). "In our study, we identified CYP3A4 as being dowregulated only in the HCV tumor group." (PMID 36557005, 2022). "Tumour tissues were then subjected to immunohistochemistry to assess cell differentiation, as indicated by the cytoplasmic‐to‐nuclear ratio and markers such as CYP3A4, HNF4α and albumin." (PMID 33179425, 2021). "Furthermore, Drug interactions mediated by CYP3A4 are not only closely related to clinical treatment and drug contraindications, but also an important mechanism of anti-tumor drug resistance." (PMID 34381736, 2021). "At last, we checked the protein expression distribution of these genes in The Human Protein Atlas, TTK and CYP3A4 were found to be differentially expressed in tumor and normal tissues, which TTK was overexpressed in HCC and the expression of CYP3A4 was found decreased in HCC." (PMID 34257549, 2021). "The majority of tumour cells in the drug combination‐treated tumours had morphologic evidence of the terminal hepatocyte differentiation and exhibited a uniformly higher expression of CYP3A4 and albumin staining throughout the tissue section." (PMID 33179425, 2021). "However, our work presents the significant finding that the regulation of CYP3A4 expression can be directly tied to the tumor microenvironment." (PMID 34262860, 2021). "Similarly, this finding was consistent with a previous report that CYP3A4 was identified as a tumor suppressor gene related to a poor prognosis in HCC." (PMID 35003516, 2021). "Considering the research mentioned previously, we speculate that Tan IIA combined with ADM might act as an activator of PXR, forming complexes with PXR to induce the production of the downstream protein CYP3A4, subsequently inhibiting tumor progression." (PMID 34189145, 2020). "Phenytoin, through its induction of CYP3A4 can stimulate production of reactive lipid species, which may accumulate in the tumor microenvironment, increase the oxidative stress on the tumor, and help drive the cancer towards oxidative related apoptosis." (PMID 30929156, 2020). "Furthermore, several authors have demonstrated shown that CYP3A4 has a differential expression in normal tissue vs tumor samples." (PMID 31105885, 2019). "Both CYP1A2 and CYP3A4 were predominantly observed staining in the cytoplasm of tumor cells." (PMID 28418906, 2017). "Furthermore, the CYP3A4*1B promoter variant is linked to higher tumor grade and advanced tumor stage due to ineffective androgen deactivation rather than direct regulation of AR expression." (PMID 41514571, 2025). "However, as aging progresses and CYP3A4 expression further increases, this balance may shift toward oxidative damage and tumor promotion." (PMID 41142201, 2025). "However, this residual GGA production appears insufficient to exert robust tumor-suppressive effects, suggesting that CYP3A4-mediated compensation may operate below the threshold required for effective chemoprevention." (PMID 41142201, 2025).